LRRC37A3 (leucine rich repeat containing 37 member A3)
Synonyms: KIAA0563; FLJ34306
Tractability: Antibody: UniProt predicts a signal peptide or a membrane-spanning region.
Gene: Protein-coding gene on chromosome 17 (64,854,130 to 64,919,480, reverse strand). Ensembl gene ENSG00000176809.
Subcellular location: Membrane
Subcellular location (Human Protein Atlas): Vesicles
Gene Ontology:
Cellular component: membrane
Genetic constraint (gnomAD): Loss-of-function variants: 21 observed, 63.28 expected, observed/expected ratio (o/e) 0.33, 90% interval 0.23 to 0.48. The synonymous counts are far from expectation, so gnomAD's model fits this gene poorly and the ratio says little. Missense variants: 665 observed, 1,027 expected, observed/expected ratio (o/e) 0.65, 90% interval 0.61 to 0.69. Synonymous variants: 291 observed, 388.82 expected, observed/expected ratio (o/e) 0.75, 90% interval 0.68 to 0.82.
Homologues: Orthologues: rat Prp2l1 (44% identical), mouse Lrrc37a (41% identical), mouse Lrrc37 (40% identical), rat Lrrc37a (39% identical). Paralogues in human: LRRC37A2 (98% identical), LRRC37A (97% identical), LRRC37B (39% identical).